NFYA (nuclear transcription factor Y subunit alpha)
Diseases named in the same sentence as NFYA in open-access papers (continued):
Sharing a sentence is not in itself a finding about the gene and the disease.
cancer (42 papers, 2016 to 2026). A tumor composed of atypical neoplastic, often pleomorphic cells that invade other tissues. "The transcription factor NFYA regulates gluconeogenesis in the normal liver tissue, but the function of the NFYA-gluconeogenesis axis in cancer and the functional differences of NFYA splicing variants in the regulation of gluconeogenesis is still unclear." (PMID 36092708, 2022). "Our bioinformatic analysis shows solid evidence to propose oncogenic role of H2A.Z in CC, by regulating the expression of cancer-associated genes at promoter and enhancer levels, as well as its association with TFs such as RNA Pol II, NFYA, and NRF1." (PMID 35317119, 2021). "Nuclear transcription factor Y subunit beta and nuclear transcription factor Y subunit alpha genes were significantly associated with the upregulated genes in mice treated with the combination of cancer therapeutics and B. bre JCM92 (boosted group)." (PMID 33668827, 2021). "Collectively, our findings establish BRD2 as a critical mediator of pan-cancer adaptive resistance to BETi and identify NFYA as a novel transcriptional regulator of this process." (PMID 42069518, 2026). "Although it has been reported that SP1 and NFYA are transcription factors that regulate the transcription activity of Snd1 in cancer cells, in this study, we demonstrated that both of them did not affect Snd1 transcription activity in VSMCs." (PMID 38279051, 2024). "NFYA is a transcription factor that was reported to promote the development of many cancers, including HCC." (PMID 35051313, 2022). "It was reported that NFYA was upregulated in cancer stem cells of HCC." (PMID 35051313, 2022). "However, an experimental approach is needed to verify the cooperation between H2A.Z and TFs such as SP2, ZNF384, YY1, NRF1, and NFYA in the transcriptional misregulation in cancer." (PMID 35317119, 2021). "As a transcription factor, NFYA binds to the CAAT box in promotors of many genes in eukaryotes and functions as a regulator of their overexpression in several types of cancer." (PMID 29983834, 2018). "The cancer-dependent regulation of C12orf49 gene expression through nuclear transcription factor Y subunit alpha (NFYA) is not yet known, however, there is evidence of its role in the trans-activation of some cancer-promoting genes." (PMID 37373333, 2023). "In addition, we also found significant positive correlations of gene expressions between FOXM1 and the NFY subunits (NFYA, NFYB or NFYC) in several cancer types." (PMID 32858881, 2020).
tumor (33 papers, 2009 to 2025). "NFYA-deficient cells showed a repressed carcinogenic phenotype, represented by a suppressed ability to grow cells and form spheres and tumours." (PMID 37268670, 2023). "The short-isoform of NFYA transcriptionally amplifies the survival and tumor cell proliferation-associated genes." (PMID 37189841, 2023). "Two splicing variants exist in NFYA that exhibit high expression in many human tumour types." (PMID 37268670, 2023). "The high level of NFYA in the tumor was significantly associated with an unfavorable RFS." (PMID 35051313, 2022). "We further identified NFYA, known to promote tumor progression in TNBC, as the most enriched transcription factor targeting over 50% of the upregulated genes." (PMID 37189841, 2023). "This study revealed an essential role for NFYA in regulating lipid metabolism and the regulatory mechanisms of tumour malignant behavior by the NFYA-lipogenesis axis, demonstrating the importance of the lipid metabolic pathway as a therapeutic target for TNBC." (PMID 37268670, 2023). "The results showed that the tumour tissues derived from NFYA+/+ SUM159 cells highly expressed these genes." (PMID 37268670, 2023). "In contrast, tumour tissues derived from NFYA−/− SUM159 cells showed reduced expression of these genes." (PMID 37268670, 2023). "To investigate the anti-tumor effects of gluconeogenesis regulation by NFYA on HCC, we examined the expression of NFYA and gluconeogenic enzymes in five different HCC cell lines." (PMID 36092708, 2022). "In this study, we investigated the functional importance of NFYA splicing variants for the anti-tumor effects of gluconeogenesis in HCC and found that the expression of NFYA, especially NFYAv2, is upregulated in HCC in response to glucose deprivation." (PMID 36092708, 2022). "Given that the anti-tumor effects of NFYAv2 are achieved through gluconeogenesis and that NFYA regulates gluconeogenic enzyme PCK1 expression in hepatocytes, we next examined the expression of PCK1 to determine how the NFYAv2 regulates gluconeogenesis in HCC." (PMID 36092708, 2022). "NFYA also contributes to HCC by enhancing the generation of a tumor‐specific transcript of lin‐28 homolog B (ILN28), a gene highly expressed during embryogenesis but silent after birth." (PMID 35051313, 2022). "NFYA expression is significantly decreased in most tumor kidney samples compared to control kidney samples." (PMID 19265534, 2009). "Here, we describe how NFYA regulates malignant behavior of tumour cells." (PMID 37268670, 2023). "MiR-302a-3p and miR-3130-3p restrained tumor progression by decreasing expression of downstream gene NFYA, which could have acted as a transcriptional factor for SATB1." (PMID 29467441, 2018). "NFYA was found to show various functions in tumor development." (PMID 29467441, 2018). "Although these findings led us to hypothesize that NFYA could play an essential role in tumor suppression of HCC through the regulation of gluconeogenesis, the regulatory mechanism for gluconeogenesis by NFYA in HCC and the functional differences between NFYA splicing variants remain unclear." (PMID 36092708, 2022). "Moreover, ISH and IHC were performed to detect the expression of LINC01016, miR-302a-3p/miR-3130-3p, NFYA, and SATB1 in xenograft tumor tissues formed by Ishikawa cells." (PMID 29467441, 2018).
infection (10 papers, 2008 to 2025). The state of being infected such as from the introduction of a foreign agent such as serum, vaccine, antigenic substance or organism. "In infection-susceptible cells, genes regulated by the transcription factors NFYA/NFYB, ZBTB7A, and PBX3 were downregulated both in the presence and absence of infection." (PMID 40725231, 2025). "Our findings showed that the downregulation of genes controlled by the transcription factors NFYA/NFYB, ZBTB7A, and PBX3 was a common feature of cells susceptible to infection both before and after exposure." (PMID 40725231, 2025).
neurodegenerative disease (2 papers, 2021 to 2024). A disorder of the central nervous system characterized by gradual and progressive loss of neural tissue and neurologic function. "NFYA is reduced in some polyglutamine expansion neurodegenerative diseases, and conditional deletion in mouse neurons induces neurodegeneration with ubiquitin/p62 accumulation." (PMID 33981329, 2021). "NFYA plays a role in the regulation of neurodegenerative diseases and haematopoietic stem cells." (PMID 39840278, 2024).
metabolic disorders (1 paper, 2026). "Particularly, the identification of serine 325 as the phosphorylation site mediating NFYa degradation recognized a key regulatory molecular switch, as well as a potential target for modulating NFYa activity in metabolic disorders or developmental abnormalities." (PMID 41536305, 2026).
NFYA also shares sentences with these, for which no sentence is quoted: neuroblastoma (6 papers); angiomyolipoma (2); diabetes mellitus (2); gastric adenocarcinoma (2); lung adenocarcinoma (2); melanoma (2); ovarian carcinoma (2); Spinocerebellar Ataxia 17 (2); squamous cell carcinoma (2); triple-negative breast carcinoma (2); viral infection (2); adenocarcinoma (1); Cirrhosis (1); coeliac disease (1); colon adenocarcinoma (1); congenital heart disease (1); cyst (1); diabetic retinopathy (1); embryonic carcinoma (1); endometriosis (1); gastric tumors (1); glioma (1); heart failure (1); kidney angiomyolipoma (1); kidney tumors (1); leukemia (1); malaria (1); non-small cell lung carcinoma (1); Obesity (1); pancreatic cancer (1).
A further 4 diseases each share a sentence with NFYA in 1 paper.